ZEB1 (zinc finger E-box binding homeobox 1)
Diseases named in the same sentence as ZEB1 in open-access papers (continued):
Sharing a sentence is not in itself a finding about the gene and the disease.
cancer (continued). "Therefore, pharmacological inhibition of EMT or inhibition of the functions of EMT transcription factors, for example Twist, ZEB1 and Snail, may be important to cancer management." (PMID 33159487, 2020). "Similarly, ZEB1 was involved in Wnt/β-catenin signaling to promote cancer cell metastasis." (PMID 32014049, 2020). "Thus, identifying the AGR2/ miR-200c /ZEB1 axis and its involvement in cancer progression could represent a new strategy leading to more efficient targeting and/or preventing the development of metastasis." (PMID 32570918, 2020). "Therefore, ZEB1 is an encouraging prospective therapeutic target, ZEB1 inhibition may decrease the proliferation or metastasis of cancer cells." (PMID 32667627, 2020). "Concerning the response of identified cancer cells to radiation, it is suggested that ZEB1 may both hinder the formation of oncogene-induced DNA damage by inhibiting oxidative stress and promote the clearance of DNA breaks by activating DDR, protecting cancer cells for survival." (PMID 32014049, 2020). "TF ZEB1 could positively regulate target gene TGFBR3 to promote cancer cell EMT and migration." (PMID 31126066, 2019). "Interestingly, recent studies have shown that ZEB1 could upregulate the expression of PD-L1 to improve the immune evasion in cancer cells." (PMID 31570691, 2019). "In addition, using a migration wound-healing assay, we observed that the migration of PyMT-cancer cells was substantially reduced in the presence of the conditioned medium generated from ZEB1-deleted CAFs relative to the conditioned medium from control CAFs at 36 h of culture." (PMID 31324807, 2019). "Furthermore, the downstream protein of PI3K/AKT-signaling pathway, such as c-Myc and ZEB1 could regulate proliferation, migration, and invasion in cancer cells." (PMID 30631050, 2019). "Notably, ZEB1 and ZEB2 are implicated in chemoresistance in a variety cancer types." (PMID 29849953, 2018). "Moreover, reduced Zeb-1 inhibited EMT of cancer cells per se and decreased tumorigenesis." (PMID 29499765, 2018). "There is evidence to suggest that high levels of SNAIL and ZEB1 proteins are correlated with cancer disease relapse and short-term survival in many different typologies of cancer, highlighting how the EMT process might be one of the key reasons for dismal clinical outcomes in patients." (PMID 28895920, 2017). "Besides, ZEB1 has been reported to help cancer cells develop resistance to radiation via stabilizing CHK1, while ZEB2 could protect cancer cells from UV or cisplatin induced apoptosis." (PMID 28416756, 2017). "All MZF1 shRNAs, 4 out of 5 SOX10 shRNAs, and 2 of 3 ZEB1 shRNAs exhibited a strong effect on nearly all 212 cell lines, suggesting that these 3 TFs could be functionally essential in cancer cells." (PMID 28423538, 2017). "While many properties of cancer, including cell migration, invasion, metastasis, stem-like properties, and therapeutic resistance, have been ascribed to EMT, only a few previous studies have linked EMT or ZEB1 expression to cell growth in suspension cultures or anchorage-independent growth." (PMID 28786996, 2017). "The ‘poised’ chromatin state of ZEB1 in which the ZEB1 promoter simultaneously displays epigenetic marks of both active and repressed chromatin may enhance cellular plasticity among cancer stem cells (CSCs) and non‐CSCs and consequently spike tumorigenic potential." (PMID 28548388, 2017). "In VM‐positive cancer cells, ZEB1 could indirectly induce stemness maintenance more efficiently." (PMID 27027258, 2016). "In contrast, the luminal miRNAs targeted transcription factors that controlled EMT (ZEB1/2), and biomarkers associated with fibrosis and actin cytoskeleton (collagens), and basal cancer biology (IL6, EGFR, STAT3), all of which are suppressed in luminal cancers." (PMID 27845906, 2016).
cancer (continued). "Module 5 contains known EMT inducers ZEB1, SNAI2, and TCF4 (E2.2), as well as multiple other genes known to be important in focal adhesion, extracellular matrix interaction, extracellular matrix organization, and markers of cancer-associated fibroblasts (PDGFRB, PDGFRA)." (PMID 27287041, 2016). "Recent study also shows that ZEB1, a transcription repressor of differentiation-associated genes, turns its function into a transcriptional co-activator of a common ZEB1/YAP target genes through interacting with YAP and therefore leading to aggressive cancer phenotype." (PMID 27411336, 2016). "Considering the importance of ZEB1 in EMT initiation and chemoresistance, our study indicates that FLASH-mediated ZEB1 regulation could be exploited to design therapies directed toward ZEB1 degradation in cells undergoing EMT to block this key step in cancer progression." (PMID 27526108, 2016). "Thus, we postulated the atypical E3 ubiquitin ligase SPFFbxo45 complex might also make contributions to EMT processes by mediating the ubiquitin-dependent degradation of EMT-TFs, particularly Zeb1 and Zeb2 proteins in cancer cells." (PMID 25460509, 2015). "Furthermore, our data comparing patient-derived cancer cells indicate that high ZEB1/low miR-203 expression might predict a favorable effect of mocetinostat in sensitizing cancer cells." (PMID 25872941, 2015). "ZEB1 is a known driver of epithelial-to-mesenchymal transition (EMT), a phenotype associated with cancer cells that are typically prone to metastasis, drug resistance and poor clinical outcome, and which represent potential therapeutic targets for cancer progression." (PMID 25890268, 2015). "Thus, depending on the ZEB1 levels in cancer cells, this loop could stabilize either mesenchymal or epithelial differentiation, accounting for the phenotypic heterogeneity viewed in tumors and metastases." (PMID 25033876, 2014). "Therefore, correlations between CDH1, CDH2, and ZEB1 genes that have been described in cancer may also exist in early zebrafish development." (PMID 23667256, 2013). "Another role of ZEB1 in cancer cells may be the circumvention of replicative senescence." (PMID 24281177, 2010). "The epithelial-mesenchymal transition (EMT) drives cancer progression, regulated by transcription factors (TFs) such as SNAI1, SNAI2, ZEB1, ZEB2, and TWIST." (PMID 41481650, 2026). "The expression levels of ACBD3 are positively correlated with epithelial marker E-Cadherin (CDH1) and negatively correlated with mesenchymal marker Vimentin (VIM) or Zinc Finger E-Box Binding Homeobox 1 (ZEB1) in TCGA LUAD cohort and cancer cell lines." (PMID 40189704, 2025). "These genes—Derlin1, ZEB1, CNN3, and PSMD10 (gankyrin)—were selected based on previous reports of their overexpression in CC and their established roles in cancer progression, metastasis, and immune regulation." (PMID 40771905, 2025). "It does so by modulating ZEB1 expression and m6A RNA methylation, offering valuable insights into the therapeutic potential of RSV in counteracting environmentally induced cancer progression." (PMID 40969596, 2025). "First, we noted that CDS1-high cancer cells express high levels of the epithelial marker gene E-cadherin (CDH1), whereas CDS1-low cancer cell lines express mesenchymal markers like ZEB1, ZEB2 and vimentin (VIM) 48,49." (PMID 40615674, 2025). "It is known to target key transcription factors such as ZEB1 and ZEB2, which are pivotal in promoting EMT and enhancing the invasive potential of cancer cells." (PMID 39859424, 2025). "In this study, we demonstrated that ZEB1 controls ITIH2 and other components involved in the reconstruction of the HA matrix, propelling changes in the lung TME that enhance cancer cell migration and invasion." (PMID 40178908, 2025).
cancer (continued). "ZEB1 (zinc finger E-box binding Hox 1) and ZEB2 functioned as transcription factors, stimulating invasion and migration by enhancing EMT in cancer cells." (PMID 40075616, 2025). "Spontaneous activation levels of ZEB1 protein and RNA expression allowed the designation of Huh7, HepG2, HuCC-T1, HuCC-A1 and TFK1 as ZEB1low and Snu475, Snu387, Snu423 as ZEB1high cancer cell lines." (PMID 40830586, 2025). "For example, miR-200 is emerging as a novel star miRNA by targeting the transcription factors ZEB1 and ZEB2 to inhibit EMT and thereby prevent further development of malignant tumors." (PMID 40004224, 2025). "Given the pivotal role of EMT in cancer progression and the well-established function of ZEB1 as a key EMT regulator, we further explored the potential interplay between ZEB1 and MYH11 in CRC cells." (PMID 40918458, 2025). "An example is the mesenchymal transcription factor ZEB1, depletion of which induces CDS1, but also reduces cancer cell survival." (PMID 40615674, 2025). "Treatment with the NTN1 antibody decreased FAK phosphorylation, downregulated ZEB1 and SOX9, reduced Ki-67+ proliferating cancer cells, and also decreased PGP9.5+ and TH+ nerves." (PMID 40777309, 2025). "The ZEB1 gene is known to be involved in EMT, a process that is crucial for various physiological and pathological events, including cancer metastasis and tissue repair." (PMID 39129166, 2025). "The expression of EMT inducing transcription factors such as ZEB1, SNAIL1 and 2 by cancer cells initiates the expression of stem cell markers SOX2, BMI1 and OCT4." (PMID 41190163, 2025). "ZEB1 is a key transcription factor in EMT, endowing cancer cells with an invasive, mesenchymal-like phenotype and serving as a predictor of poor clinical prognosis in most cancers." (PMID 40304000, 2025). "It has been reported that miRNA-200c closely interacts with the ZEB1 and ZEB2 proteins and prevents invasion in cancer cells through this complex." (PMID 40728965, 2025). "Radiation responses and cancer metastasis influence EMT through the TGF‐β, Wnt/β‐catenin, and Notch signaling pathways, involving transcription factors such as Snail, Slug, ZEB1/2, and Twist." (PMID 40895189, 2025). "In contrast, levels of several epithelial‐mesenchymal transition (EMT)‐ and cancer stem cell (CSC)‐related markers including Nestin, ALDH1, ZEB1, Slug, and Twist 1 were lower in OE‐ALKATI cells when compared to mock cells." (PMID 40387841, 2025). "ZEB1, a key regulator of EMT, is activated in cancer cells by CCL18 secreted by TAMs, leading to the increased expression of genes involved in extracellular matrix degradation, such as MMP9, and promotes the recruitment of additional TAMs by inducing CCL2." (PMID 40362280, 2025). "In this cancer, USP18 enhances the protein stability of zinc finger E-box-binding homeobox 1 (ZEB1) through the decreased ubiquitination of ZEB1, increasing the migration and invasion abilities of ESCC cells." (PMID 38675828, 2024). "As a representative lncRNA, its unique target ZEB1 can combine with EMT-related pathways and play a particularly important role in cancer metastasis, invasion, and cell cycle regulation." (PMID 39857631, 2024). "The melatonin treatment reduced the expression levels of ZEB1 and ZEB2 and some other EMT-relevant factors, thus decreasing the EMT and inhibiting the invasion properties of SKOV3-derived cancer stem cells." (PMID 38473317, 2024). "NF-kB activation induces transcription of downstream genes involved in principal hallmarks of cancer; among of these, there are SNAI1 and ZEB1 that play a key role in EMT process." (PMID 38773406, 2024). "It has been reported that the downstream genes of ZAFS1/miR-150 includes VEGFA, ST6GAL1, ZEB1 and RAB9A in cancer cells [16,]." (PMID 39296014, 2024). "Expression profiling of EMT regulators showed gradual over-expressions of ZEB1 (8, 20, and 42 folds) and ZEB2 (4, 10, and 18 folds) in respective histological cancer grades." (PMID 38751602, 2024).
cancer (continued). "According to several reports, specific miRNAs directly target mRNAs of ZEB1 and ZEB2 in cancer cells by upregulating E- cadherin and reducing cell motility." (PMID 39450256, 2024). "ZEB1 is a major regulator of EMT that promotes cell proliferation, differentiation, and migration, and plays important roles in development, cancer progression, and tissue fibrosis." (PMID 38822380, 2024). "EPLIN has been reported as a negative regulator of EMT in several cancer types by regulating several contributors, such as SNAIL, SLUG and ZEB1/216,18." (PMID 39730634, 2024). "Transcription factors such as Snail, Zeb1, Slug, Twist, and FOXC1 can also act as inducible factors in EMTs, implying that they are potential targets for cancer treatment." (PMID 38469234, 2024). "These compelling findings strongly support the notion that ZEB1 plays a pivotal role in promoting the proliferation and invasion of CRC, thereby contributing to cancer progression." (PMID 39193340, 2024). "CRISPR–Cas9 essentiality screens (CERES) identify Zeb1 as an important gene in MDA-MB-231 cells, one of the most ferroptosis sensitive cancer cell lines." (PMID 39009641, 2024). "In vitro and in vivo experiments showed similar functions of ZEB1 and ZEB2, that is, both inhibited cell proliferation, likely by inducing CDK inhibitors, and both promoted anti‐cancer drug resistance and motile properties." (PMID 39362647, 2024). "In this study, we analyzed the influence of altered ZEB1 and SNAI1 expression levels on cancer progression using a retrospective cohort of 51 intermediate-risk PCa tumors from FMRP-USP, Brazil." (PMID 38672562, 2024). "The induction of EMT leads to cancer metastasis via EMT transcription factors including Snail, Slug, Twist, Zeb1, and Zeb2." (PMID 38393059, 2024). "In contrast, ZEB1 and ZEB2 inhibit the expression of the miR-200 family, thus creating a feedback loop that promotes EMT and cancer cell aggressiveness." (PMID 39224263, 2024). "At the same time, miR-200b-3p targeting ZEB1 inhibits EMT and participates in cancer invasion and migration." (PMID 38702771, 2024). "In conclusion, our study highlights the significance of targeting CD73 in cancer beyond its role in the immune system and emphasizes the importance of understanding its interactions with EMT markers, such as ZEB1." (PMID 38388432, 2024). "The transcription factors Snail, ZEB1/2, and TWIST, along with miRNA, epigenetic regulators, and alternative splicing, are regulated by these pathways during cancer progression." (PMID 39450256, 2024). "For example, reprogramming TAMs using a ZEB1 antagonist and blocking the CD47-SIRPα pathway are state-of-the-art “normalization cancer immunotherapy” strategies that can synergistically restore the antitumour properties of immune cells in the TME." (PMID 38183060, 2024). "Instead, a high expression of NANOG and Zeb-1 and an expression of CDH-1, similar to that detected in ground control cells characterized BR95 cancer cells, well identify their mesenchymal character." (PMID 39451527, 2024). "In all, this study demonstrates that BRCC3 can increase the stability of ZEB1, upregulate ZEB1 expression, and promote the proliferation, migration, invasion, EMT, and metastasis of TNBC cells, providing a new direction for cancer therapy." (PMID 38449391, 2024). "We found a correlation between PROM2 expression and the three EMT markers ZEB1, SNAI1 and TWIST1 in both cancer types." (PMID 38515278, 2024). "ZEB1, a ZEB family member, activates cancer stem cells, regulates apoptosis, promotes angiogenesis, and resists chemotherapy." (PMID 37989078, 2024).
cancer (continued). "According to these studies, circRNAs regulate ZEB1 and ZEB2, and more research is needed to understand ZEB2 regulation by circRNAs in cancers." (PMID 38733529, 2024). "The transcription factors regulating EMT, including snail family transcriptional repressor 1 (SNAI1), twist family bhlh transcription factor 1 (Twist1), zinc finger e-box binding homeobox 1 (ZEB1) and ZEB2, regulate cancer migration, invasion, and metastasis." (PMID 39154024, 2024). "A few studies showed the clue that stemness factors SOX2, BMI1, OCT4, or SOX9 can be regulated by ZEB1, SNAI1, or SNAI2, thereby promoting not only stemness and metastasis of cancer cells, but also resistance to radio- and chemotherapy." (PMID 39164745, 2024). "We discovered the TFs that are sequentially and significantly upregulated as carcinoma cells progress through the EMT process and demonstrated that ZEB1 and ZEB2 play pivotal roles in initiating and sustaining the EMT phenotype." (PMID 39256881, 2024). "These EMT-TFs, mainly including SNAILl, Twist-related protein 1 (TWIST1), ZEB1 and ZEB2, are pivotal in activating CAFs in different cancer contexts." (PMID 38124183, 2023). "ZEB-1 is an inducer of EMT and cancer progression by downregulating E-cadherin, leading to advanced disease or metastasis." (PMID 36674719, 2023). "The evidence that ERK1/2 activate EMT core transcription factors like SNAIL, SLUG, TWIST, ZEB1, and ZEB2 is mainly obtained from cancer cell studies." (PMID 37009481, 2023). "Cancer cells in the mesenchymal state show enhanced PUFA-PL synthesis, possibly resulting from ZEB1-mediated upregulation of PPARγ, which ia a major regulator of lipid metabolism in liver." (PMID 37795022, 2023). "Analysis of Biological General Repository for Interaction Datasets (BioGRID) uncovers that DCAF15 interacts with ZEB1, a key transcription factor regulating EMT and migration of cancer cells." (PMID 36805336, 2023). "The zinc-finger E homeobox-binding (ZEB) family of TFs contains two members, ZEB1 and ZEB2, which play a central role in cancer cell plasticity." (PMID 37370762, 2023). "ZEB1 and ZEB2 are highly expressed in several cancers, including BC, pancreatic cancer, HCC, and lung cancer." (PMID 37444447, 2023). "MiR-200 family miRNAs repress the expression of ZEB1 and ZEB2, thereby preserving the epithelial phenotype of cancer cells." (PMID 37460540, 2023). "The EMT core regulators ZEB1, ZEB2, Snail, Slug and TWIST1 are up-regulated in claudin-low cancers independently of the status of ER expression." (PMID 37504297, 2023). "These authors also found that PTK6 promoted the development and metastasis of cancer by increasing STAT3 phosphorylation and ZEB1 expression." (PMID 37932734, 2023). "ZEB1 plays a pivotal role in epithelial-to-mesenchymal transition (EMT), (cancer) cell stemness and cancer therapy resistance." (PMID 38139138, 2023). "Transwell/ Boyden chamber data indicate, that the migratory activity of ZEB1-KO was markedly diminished in comparison to wildtype cells, which is in agreement with the pivotal role of ZEB1 in EMT, cancer progression and metastasis formation." (PMID 38139138, 2023). "Due to its role in down-regulating E-CADHERIN (CDH1) expression, ZEB1 is commonly known as a driver of EMT, cancer progression and metastasis formation." (PMID 38139138, 2023). "Nevertheless, since the role of ZEB1 in macrophages is still emerging, future research is needed to determine whether prolonged ZEB1 overexpression in myeloid cells using nanoparticles can have deleterious effects and/or potentially contribute to cancer development." (PMID 38097578, 2023). "For example, miR-200 family negatively regulates ZEB1 and ZEB2, and deceased during EMT in cancer cells." (PMID 36823234, 2023).